PHACTR1 (phosphatase and actin regulator 1)
Diseases named in the same sentence as PHACTR1 in open-access papers (continued):
Sharing a sentence is not in itself a finding about the gene and the disease.
myocardial infarction (13 papers, 2014 to 2024). Gross necrosis of the myocardium, as a result of interruption of the blood supply to the area, as in coronary thrombosis. "The non-coding locus at 6p24 located in Intron 3 of PHACTR1 has consistently been implicated as a risk allele in myocardial infarction and multiple other vascular diseases." (PMID 35653516, 2023). "For CAD, one of the most robust reported risk loci is at the PHACTR1 gene locus where several studies have identified intronic SNPs that are associated with the risk of myocardial infarction, coronary stenosis and coronary calcification." (PMID 27187934, 2016). "Further, PHACTR1 gene polymorphisms have been associated with several diseases, including hypertension, diabetes mellitus, cervical artery dissection and myocardial infarction." (PMID 27517945, 2016). "SNPs at the PHACTR1 locus are associated with the specific phenotypes of early onset myocardial infarction, coronary artery calcification and with an intermediate phenotype of impaired central hemodynamic indices, indicating abnormal vascular stiffness." (PMID 27187934, 2016). "PHACTR1 variants that influence the risk of myocardial infarction (MI) in genome-wide association studies (GWAS) were identified." (PMID 25123136, 2014). "Of these, PHACTR1 has been associated in early-onset myocardial infarction in GWAS irrespective of ethnic backgrounds." (PMID 26098115, 2015). "PHACTR1 protein regulates the remodeling of the heart after myocardial infarction (MI), increasing its expression and the total protein levels after the event." (PMID 37761953, 2023).
Hypertension (11 papers, 2016 to 2026). The presence of chronic increased pressure in the systemic arterial system. "In this analysis, the higher number of PHACTR1 rs9349379 G andLMOD1 rs2820315 T alleles, as well as age, male sex, hypertension, higher BMI, diabetes and low HDL serum level, were independent factors predisposing to unstable angina." (PMID 35054067, 2022). "With regard to the PHACTR1 gene, studies have found that rs9369640 was related to hypertension, rs1223397 was suggestively associated with PP, and rs9349379 was linked to SBP." (PMID 32420588, 2020). "The PHACTR1 association with hypertension in this PheWAS is supported by the recent GWAS literature for blood pressure." (PMID 31891604, 2019). "One carrier from the US was affected by hypertension, nonetheless, given the high frequency of hypertensive patients in the US cohort (60.4%), we may probably exclude a direct or critical effect of PHACTR1 coding variability on hypertension." (PMID 33727568, 2021). "More studies have displayed that the polymorphisms of the PHACTR1 gene have been related to the pathogenesis of endothelial dysfunction and vascular diseases, i.e., CHD, MI and hypertension, etc., and endothelial dysfunction makes an important contribution to high PP." (PMID 32420588, 2020). "Among the non-LDL-C associations, PheWAS-identified PHACTR1 rs9349379 was associated with the three phenotype classes of smoking, diabetes, and hypertension in opposing directions." (PMID 31891604, 2019). "Finally, the genetic risk locus on chromosome 6p24, which contains PHACTR1 and EDN1 genes, is associated with multiple vascular diseases, including CAD, migraine headache, coronary calcification, hypertension, fibromuscular dysplasia, microvascular angina, and arterial dissection." (PMID 38627847, 2024).
fibromuscular dysplasia (10 papers, 2016 to 2024). A disorder characterized by fibrous thickening of the arterial wall resulting in narrowing of the arterial lumen. "It has been reported in the literature that PHACTR1 is a genetic susceptibility locus for fibromuscular dysplasia (FMD)." (PMID 33421990, 2021). "Our study describes for the first time the genetic association of rs9349379, a common variant in PHACTR1, with arterial fibromuscular dysplasia (FMD)." (PMID 27792790, 2016). "Variants in the PHACTR1/EDN1 gene locus have been associated with vasculopathies including spontaneous coronary artery dissection (SCAD), fibromuscular dysplasia, and cervical artery dissection." (PMID 38259468, 2023). "The search included keywords, not limited to “Spontaneous coronary artery dissection”, “SCAD”, “Fibromuscular Dysplasia”, “FMD”, “Spontaneous coronary artery dissection and Fibromuscular Dysplasia”, and “PHACTR1”." (PMID 38883987, 2024).
cervical artery dissection (7 papers, 2016 to 2026). A tear within the wall of any of the arteries of the neck (carotid artery or vertebral artery) and that allows blood to separate the wall layers. "PHACTR1 and LRP1 were also associated with cervical artery dissection and spontaneous coronary artery dissection, and LRPI was additionally associated with abdominal aortic aneurysm 23–25." (PMID 34654805, 2021).
Stroke (7 papers, 2013 to 2025). Sudden impairment of blood flow to a part of the brain due to occlusion or rupture of an artery to the brain. "Some of the DECs we identified are encoded by genes such as Phactr1, Fgfr1, and others that have been shown to be associated with stroke." (PMID 41226594, 2025). "Replication of SNPs from related cardiovascular GWAS studies found one novel association with gene PHACTR1 which suggests that detection of any new genetic risk variants will rest on proper stroke subtyping." (PMID 23505425, 2013). "Nonetheless, rare variants in PHACTR1 RPEL domains may influence the stroke outcome and are worth investigating in a larger cohort of small vessel ischemic disease patients, different ischemic stroke subtypes and with functional studies." (PMID 33727568, 2021).
diabetes (5 papers, 2015 to 2022). "In the discovery phase of this stratified analysis, 3 known CAD loci reached genome-wide significance: ADAMTS7 in subjects with T2D and 9p21.3 and PHACTR1 in the analysis of subjects without diabetes mellitus." (PMID 33321069, 2020).
endothelial dysfunction (4 papers, 2015 to 2025). In vascular diseases, endothelial dysfunction is a systemic pathological state of the endothelium (the inner lining of blood vessels) and can be broadly defined as an imbalance between vasodilating and vasoconstricting substances produced by (or acting on) the endothelium. "In ECs, PHACTR1 is inextricably linked with endothelial inflammation and endothelial dysfunction; however, the precise role of PHACTR1 in regulating endothelial function remain controversial." (PMID 36091033, 2022). "PHACTR1 is an important CAD risk gene that mediates endothelial dysfunction." (PMID 36091033, 2022). "In this manner, PHACTR1 impairs endothelial NO production, which in turn leads to endothelial dysfunction." (PMID 36091033, 2022). "Next, we aim to explore the potential molecular mechanism whereby PHACTR1 triggers endothelial dysfunction." (PMID 36091033, 2022). "In conclusion, our study demonstrates the role of PHACTR1 in endothelial dysfunction, in terms of endothelial inflammation and endothelial NO production by activating NF-κB and decreasing Akt/eNOS activity, respectively." (PMID 36091033, 2022). "Further studies are warranted to confirm the precise mechanism of PHACTR1 in driving endothelial dysfunction." (PMID 36091033, 2022). "Therefore, the purpose of the present study is to evaluate the effect and mechanism of PHACTR1 overexpression on endothelial dysfunction by focusing on inflammation and nitric oxide (NO) production." (PMID 36091033, 2022). "This suggests that PHACTR1 overexpression may aggravate endothelial dysfunction." (PMID 36091033, 2022). "However, it remains largely unclear how PHACTR1 is involved in endothelial dysfunction." (PMID 36091033, 2022).
West syndrome (4 papers, 2020 to 2021). "A recent study demonstrated the de novo PHACTR1 mutations to be the cause of West syndrome in two Japanese patients." (PMID 33463715, 2021). "Here we used whole‐exome sequencing (WES) to identify a novel mutation in PHACTR1 that occurred de novo in a proband with multifocal epilepsy with infantile spasms and hypsarrhythmia." (PMID 33463715, 2021). "Here we describe a de novo mutation, L519R, in PHACTR1 in a sporadic case of multifocal epilepsy with infantile spasms and hypsarrhythmia." (PMID 33463715, 2021). "Although authors do provide evidence for the pathogenic role of these PHACTR1 mutations in a rodent model how this relates to pathogenesis of West syndrome remained unclear." (PMID 33463715, 2021). "The genetic dominance of West syndrome Phactr1 mutations and Phactr4 R536P/humdy mutation also is consistent with Phactr-family proteins interacting with other cellular components in addition to PP1." (PMID 32975518, 2020). "PHACTR1 mutations cause functional defects in neurons related to West syndrome and other intellectual disabilities, and was hypomethylated in the reduced cognition group (−19.15%)." (PMID 32033187, 2020). "Indeed, recently, it was demonstrated that de novo mutations in PHACTR1 gene are associated with West syndrome characterized by infantile spasms, hypsarrhythmia, and mental retardation." (PMID 33463715, 2021). "Importantly, although we cannot exclude that rare coding variants in PHACTR1 functional domains may be causative or risk factors for ischemic stroke, cerebrovascular accidents have not been reported in West syndrome patients." (PMID 33727568, 2021).
coronary artery calcification (3 papers, 2016 to 2020). Calcification of the coronary artery, used as a measure of coronary atherosclerosis, a risk factor for myocardial infarction. "rs12526453 (PHACTR1) has been associated with coronary artery calcification through genome-wide association studies." (PMID 33192474, 2020). "One locus from the region on Ots10 was within phosphatase and actin regulator 1 (PHACTR1), which is a key regulator of endothelial cells and is also significantly associated with coronary artery calcification in humans." (PMID 29928295, 2018).
Coronary Artery Stenosis (3 papers, 2012 to 2016). "A GWAS performed in a Lebanese study recently confirmed the association of the PHACTR1 (rs9349379) gene polymorphism with coronary artery stenosis." (PMID 27517945, 2016). "The locus of the phosphatase and actin regulator 1 gene (PHACTR1) showed association with coronary stenosis in a discovery experiment with genome wide data in 1,949 individuals (rs9349379, OR = 1.37, p = 1.57×10−5)." (PMID 22745674, 2012).
migraine headache (3 papers, 2020 to 2025). "In MO, PHACTR1 appears to influence headache initiation through peripheral vascular contraction-dilation balance." (PMID 40826382, 2025).
breast carcinoma (2 papers, 2015 to 2020). "In melanoma and breast cancer cells Phactr1 is involved in actin dynamics, cell motility and invasive behaviour." (PMID 26098115, 2015).
Coronary artery dissection (2 papers, 2021 to 2022). Acute occurrence of a dissection (tear within the tunica intima and entry of blood into the tunica media) of a coronary artery. "Case-control studies have shown that PHACTR1/EDN1 is a risk factor for several vascular diseases, such as spontaneous coronary artery dissection (SCAD)." (PMID 36046789, 2022).
epilepsy (2 papers, 2021 to 2023). A brain disorder characterized by episodes of abnormally increased neuronal discharge resulting in transient episodes of sensory or motor neurological dysfunction, or psychic dysfunction. "Previously reported PHACTR1-mutated patients showed early-onset epilepsy and intellectual disability." (PMID 37483454, 2023). "While these data emphasize the detrimental effect of changes at PHACTR1 amino‐acid 521, further work is needed to establish the molecular basis of the connection between the p.R521C mutation and epilepsy." (PMID 33463715, 2021). "Our study adds PHACTR1 to the list of epilepsy‐related genes and contributes to the diverse molecular mechanisms of the disease." (PMID 33463715, 2021).
gestational diabetes (2 papers, 2024). Carbohydrate intolerance first diagnosed during pregnancy. "Among the pregnant women with gestational diabetes, the relative PHACTR1 levels were approximately two-fold higher compared to the healthy pregnant women: 0.046 [0.022–0.096] vs. 0.021 [0.007–0.047], respectively, (p = 0.0029)." (PMID 39000149, 2024). "Among the pregnant women with gestational diabetes, the relative quantity of hsa_circ_0002268 (PHACTR1) was approximately 120% higher than among healthy pregnant women: 0.046 [0.022–0.096] vs. 0.021 [0.007–0.047], respectively, (p = 0.0029)." (PMID 39000149, 2024).
intellectual disabilities (2 papers, 2020 to 2023). "Severe developmental delay, intellectual disability, and early-onset developmental and epileptic encephalopathy are the main features of PHACTR1-mutated patients with neurological involvement." (PMID 37483454, 2023).
ischemic stroke (2 papers, 2021 to 2023). A stroke disorder caused by obstruction of blood flow to the brain, due to thrombotic (local blood clot formation) or embolic (due to a blood clot or other material traveling from another site) event. "The lack of a significant correlation between PHACTR1 genetic variability and ischemic stroke has been supported also by our experiments in brain ischemia mouse models (BCCAS and MCAO), where we do not report Phactr1 CNVs as responsible for PcomA patency." (PMID 33727568, 2021). "However, PHACTR1 coding variability in RPEL domains are worth investigating in a larger cohort of SVID patients, in different ischemic stroke subtypes and with functional studies." (PMID 33727568, 2021).
lung carcinoma (2 papers, 2021 to 2022). "Also, for PHACTR1 and ANKS1B potential roles in lung cancer have been described before." (PMID 33953302, 2021).
type 2 diabetes (2 papers, 2014 to 2015). "SNP rs12526453 on chromosome 6p24.1 located in PHACTR1 showed directionally consistent associations with CAD risk in type 2 diabetes." (PMID 25123136, 2014). "The associations between several variables and outcome were not replicated in the validation group (PHACTR1 genotype, type 2 diabetes, systolic blood pressure and heart rate on admission, TIMI flow grade after procedure)." (PMID 26086777, 2015).
acute coronary syndrome (1 paper, 2022). Signs and symptoms related to acute ischemia of the myocardium secondary to coronary artery disease. "The aim of this case-control association study was to evaluate the associations between the occurrence of acute coronary syndromes in the form of unstable angina and SNPs within the PECAM1, COL4A2, PHACTR1 and LMOD1 genes." (PMID 35054067, 2022).
adenovirus infection (1 paper, 2022). "We then treated endothelial cells with different doses of RES for 12 h, followed by adenovirus infection for another 24 h to overexpress PHACTR1." (PMID 36364780, 2022).
Arterial stenosis (1 paper, 2012). Narrowing or constriction of the inner surface (lumen) of an artery. "The meta-analysis of the exploratory and the replication sets showed strong and genome-wide significant evidence for association of SNP rs9349379 in PHACTR1 with arterial stenosis in all arteries." (PMID 22745674, 2012).
cardiomyopathy (1 paper, 2015). A disease of the heart muscle or myocardium proper. "Interestingly, PHACTR1 protein levels were significantly elevated in patients with cardiomyopathy when compared to control hearts." (PMID 26098115, 2015).
cerebrovascular diseases (1 paper, 2020). "Considering the regulating function of PHACTR1 and the independent contribution of PP to cardiovascular and cerebrovascular diseases, we wondered whether polymorphisms of the PHACTR1 gene contribute to the susceptibility of high PP." (PMID 32420588, 2020).
colorectal cancer (1 paper, 2012). A primary or metastatic malignant neoplasm that affects the colon or rectum. "For the remaining genes more distant and sporadic associations have been mined in the literature for relevant diseases or other types of cancer, e.g. AMDHD1 and PHACTR1 have been linked to tobacco use disorders or RPRM with colorectal cancers." (PMID 23173873, 2012).
infarction (1 paper, 2015). A localised pathological necrosis of tissue resulting from obstruction of the blood supply usually by a thrombus, an embolus, or vascular torsion. "Both VEGF-A and TGF-β1 are crucial players in angiogenesis in post-infarction LV-remodelling, and PHACTR1 depletion has been associated with an impairment of tube formation and deranged endothelial cell function in HUVECs." (PMID 26098115, 2015). "Since PHACTR1 has been associated with early-onset MI in GWAS studies, we first studied the effect of post-infarction myocardial remodelling on Phactr1 expression in a model of acute MI in adult rats." (PMID 26098115, 2015).
Obesity (1 paper, 2015). Accumulation of substantial excess body fat. "We also identified six DMRs which mapped to obesity and related metabolic traits in the GWAS catalogue (PROX1, PHACTR1, SLC22A8, SMAD3, LCAT, DNM2)." (PMID 25651499, 2015).
unstable angina (1 paper, 2022). "The association between these alleles and unstable angina was confirmed by multivariate logistic regression analysis, in which the number of G (PHACTR1 rs9349379) and T (LMOD1 rs2820315) alleles was an independent risk factor for unstable angina." (PMID 35054067, 2022). "The results suggest an association between PHACTR1 rs9349379 and LMOD1 rs2820315 polymorphisms and the risk of unstable angina." (PMID 35054067, 2022). "The association between these alleles and unstable angina was confirmed by multivariate logistic regression analysis, in which the number of the G (PHACTR1 rs9349379) and T (LMOD1 rs2820315) alleles was an independent risk factor for unstable angina." (PMID 35054067, 2022). "The aim of this study was to evaluate the association between the PECAM1 (rs1867624), COL4A2 (rs4773144), PHACTR1 (rs9349379) and LMOD1 (rs2820315) gene polymorphisms and the risk of unstable angina." (PMID 35054067, 2022). "The presence of PHACTR1 rs9349379 G and LMOD1 rs2820315 T alleles is a risk factor for unstable angina." (PMID 35054067, 2022). "The results of our study suggest an association between PHACTR1 rs9349379 and LMOD1 rs2820315 polymorphisms and unstable angina." (PMID 35054067, 2022). "The results of this study suggest that PHACTR1 rs9349379 and LMOD1 rs2820315 gene polymorphisms are associated with an increased risk of unstable angina." (PMID 35054067, 2022). "In contrast, we found a statistically significant higher prevalence of the PHACTR1 rs9349379 G allele and the LMOD1 rs2820315 T allele in the group of patients with unstable angina." (PMID 35054067, 2022).